MOXD1 (monooxygenase DBH like 1)
Diseases named in the same sentence as MOXD1 in open-access papers (continued):
Sharing a sentence is not in itself a finding about the gene and the disease.
tumor (continued). "In order to explore the effect of MOXD1 on tumor cell self-renewal and tumor formation, we first performed a planar cloning experiment, and the result showed that MOXD1 knockdown could significantly inhibit the planar cloning ability of GBM cells." (PMID 35393406, 2022). "The MOXD1 and copper-related gene prognostic scoring system could be helpful to understand the tumor characteristics of BLCA and develop personalized immunotherapy strategies." (PMID 36620542, 2022). "In addition, we found that interactions between fibroblasts and immune cells through the IL-10 signaling pathway were significantly increased in the tumor microenvironment in patients with high MOXD1 expression compared with patients with low MOXD1 expression." (PMID 36620542, 2022). "The expression of MOXD1 is one of the characteristics of early tumor development." (PMID 35393406, 2022). "MOXD1 was expressed higher in Grade 1 tumor than that in Grade 2 tumor (P < 0.05)." (PMID 33878734, 2021). "We further analyzed MOXD1 expression in STAD based on Sample types, tumor grade, individual cancer stages, nodal metastasis status by applying UALCAN online database." (PMID 38200441, 2024). "The expression of MOXD1 in GC tumor has not been reported, and the role of MOXD1 in GC has not been studies." (PMID 38200441, 2024). "These tumor samples were, thus, not depleted of MOXD1, indeed highlighting intratumor heterogeneity and the presence of surrounding nontumor cells in these tissues." (PMID 38905335, 2024). "Furthermore, it has been reported that the early growth response protein Egr1 and the copper-dependent monooxygenase Moxd1, which were found to be significantly increased in NTBC-treated HT1 livers, are correlated to the invasiveness of HCC cells and early tumor development, respectively." (PMID 36980965, 2023).
cancer (7 papers, 2022 to 2025). A tumor composed of atypical neoplastic, often pleomorphic cells that invade other tissues. "MOXD1 expression was significantly higher in the middle and late-N3 cancers than the N0 of nodal metastasis status." (PMID 38200441, 2024). "To date, only a few studies on MOXD1 expression in malignant tumors have been published." (PMID 40989158, 2025). "MOXD1 activated cancer -related signaling pathway (MAPK, TGF-β, NOTCH and JAK/STAT)." (PMID 38200441, 2024). "Sectioning of the dissected tumors at 27 wpf revealed differences in tissue architecture, where the MYCN-TT–derived tumors comprised large amounts of connective tissue and contained smaller foci of cancer cells, while MYCN-TT + MOXD1 KO–derived tumors largely consisted of cancer cells." (PMID 38905335, 2024). "Thus, we hypothesized that the role of MOXD1 in cancer is tissue- and cell-specific, even depending on lineage commitment within the same embryonic progenitor cell population." (PMID 38905335, 2024). "The clinical database shows that MOXD1 is highly expressed in GBM cells and can promote the growth of cancer cells." (PMID 35393406, 2022). "Clinical databases showed that MOXD1 was upregulated in GBM cells and promoted cancer cell growth." (PMID 38200441, 2024). "We observed that MOXD1 does not discriminate between localized and aggressive diseases in any of these cancer types." (PMID 38905335, 2024).
MOXD1 also shares sentences with these, for which no sentence is quoted: anemia (1 paper); bacterial infections (1); breast carcinoma (1); chronic kidney disease (1); chronic obstructive pulmonary disease (1); Cirrhosis (1); glaucoma (1); Hypertension (1); metastatic disease (1); metastatic melanoma (1); neurodegenerative disease (1); Obesity (1); ocular hypertension (1).